CDK1 (cyclin dependent kinase 1)
Diseases named in the same sentence as CDK1 in open-access papers (continued):
Sharing a sentence is not in itself a finding about the gene and the disease.
cancer (continued). "This phytocompound can affect the cell cycle of cancer cells, reduce cell cycle activators, especially cyclin B, cdk1, E-cadherin, and N-cadherin and activate multiple cellular pathways, inhibit the Akt-mTOR signaling pathway thereby inhibiting the proliferation of cancer cells." (PMID 34577581, 2021). "In addition to direct alterations in CDK1-cyclin B itself, also upstream regulators of CDK1 can potentially be altered in cancer cells and can be involved in the induction of CIN." (PMID 33168930, 2021). "Cyclin dependent kinase 1 (CDK1) plays a significant role in the cell cycle process in cancers." (PMID 34298705, 2021). "However, when this cell cycle checkpoint evasion is blocked by CDK1 inhibitors, the cancer cells are less likely to survive." (PMID 34503199, 2021). "Retinoblastoma gene in cancer, another pathway associated with “Evasion of growth suppressors”, was also upregulated, with strong overexpression of pathways members leading to G1/S transition (CCNB1, CDK1) and mitotic spindle association (TTK)." (PMID 33917186, 2021). "Since BCL-2 and MCL-1 proteins may have overlapping anti-apoptotic functions with BCL-XL in cancer cells, we compared the impact of their mRNA expression levels, either alone or in combination with CDK1, CDK6 and WEE1, on the overall survival of TNBC patients." (PMID 34646365, 2021). "CDK1, a member of the CDKs, plays a critical role in different types of cancers 21, 28-30." (PMID 33867838, 2021). "Although the binding of p21 to CDK1 and its stability are involved in the nuclear accumulation of inactive CDK1–cyclin B1 complexes and the induction of apoptosis, caspase-3-mediated p21 cleavage confers DNA damage-induced apoptosis of cancer cells." (PMID 34064109, 2021). "In addition, several other studies indicate the potential of CDK1 inhibition for both cancer treatment in general, and specifically for PDAC." (PMID 34503199, 2021). "However, abnormal expression of CDK1 determines cell replication even in case of DNA damage, resulting in the proliferation of cancer cells." (PMID 35011251, 2021). "CDK1 is a cyclin-dependent kinase necessary for controlling cell cycle regulation, and its aberrant expression is responsible for uncontrolled proliferation in cancer cells as well as for genomic and chromosomal instability." (PMID 32948832, 2021). "The expression of CDK1 in different tissues could be summered as follow: nuclear CDK1 expression in cancer tissue > cytoplasmic CDK1 expression in cancer tissue > nuclear CDK1 expression in normal tissue > cytoplasmic CDK1 expression in normal tissue." (PMID 33758599, 2021). "In cancer cells, the role of CDK1 in the apoptotic pathway is more complicated." (PMID 34503199, 2021). "Furthermore, some research has suggested that CDK1 is related to anti-cancer activity and enhanced sensitivity to radiotherapy and anti-cancer drugs in HNSCC cells." (PMID 33982750, 2021). "Similarly, inhibition of CDK1, a mitosis-promoting factor, promoted the apoptosis of cancer cells through G2/M arrest." (PMID 33407832, 2021). "Based on previous studies showing that CDK1 can specifically phosphorylate AR at serine 81 to activate AR transcriptional activity, we hypothesize that the pro-cancer effect of ABCC5 is mediated by stabilizing CDK1 to activate AR phosphorylation." (PMID 33994848, 2021). "Therefore, it is possible that these receptors participate in the origin and evolution of some cancers affecting chromosome segregation during mitosis due to altered phosphorylation by the cyclin B/CDK1 complex." (PMID 33184446, 2020). "CDK1 is an effective therapeutic target for inhibitors in cancer therapy." (PMID 33505309, 2020). "And 23 of the 25 functional genes were significantly up-regulated in COAD, such as CDK1, CDK2, CDK4, CDK6, and CDK7, which can cause uncontrolled proliferation and may serve as promising targets in cancer therapy." (PMID 32680494, 2020).
cancer (continued). "Additionally, the over-expression of CDC2/CDK1 and survivin can promote cancer stem cell survival and can also promote the development of polyploidy." (PMID 32849491, 2020). "We also provide experimental evidence to support that blocking BRD4 hyperphosphorylation with CDK1 inhibitors could be employed to overcome BETi resistance in cancer." (PMID 32575711, 2020). "CDK1/2 were also identified to be activated across five cancer types." (PMID 32033228, 2020). "As cancer cells require specific interphase CDKs for proliferation, CDK1 inhibitors may provide a therapeutic benefit against RR." (PMID 32355263, 2020). "Our finding suggests that CDK1 over-activation in cancers could also contribute to BETi resistance by stimulating BRD4 hyperphosphorylation and downstream target gene expression." (PMID 32575711, 2020). "In contrast, PAK1 and CDK1 were much more abundant in cancer cells compared to stromal cells." (PMID 32917870, 2020). "CDK1 is frequently overexpressed or activated in cancer cells." (PMID 32575711, 2020). "Taken together, these data show that by inhibiting PFKFB3 K302 ubiquitination, AGPG enhanced PFKFB3 stability and therefore led to the increased accumulation of PFKFB3 in cancer cells, thereby increasing F-2,6-BP synthesis and subsequently promoting cell cycle progression by regulating p27 and CDK1." (PMID 32198345, 2020). "In conclusion, TONSL-AS1 is upregulated in EOC and may sponge miR-490-3p to upregulate CDK1, thereby promoting cancer cell proliferation." (PMID 32414422, 2020). "In addition, we acquired the expression of miRNA-205 and CDK1 in different types of cancer from starBase v3.0." (PMID 33178832, 2020). "Building on this line of reasoning, we speculated that combination of a CDK1 inhibitor and BETi can synergistically inhibit cancer cell growth." (PMID 32575711, 2020). "Both CDK1 inhibitors and BETi have been explored in clinical trials for cancer therapy." (PMID 32575711, 2020). "Pan-CDK inhibitor(s) that also targets CDK1 would be a better candidate for treating these cancers." (PMID 32214089, 2020). "Consequently, downregulation of cyclin dependent kinase 1 (Cdk1-cyclin B1) signaling resulted in cell cycle arrest, and inhibition of cancer cell proliferation in HeLa, MCF-7, PC3, SKBr3-HER2 cancer cell lines." (PMID 32296681, 2020). "BEY1107, an anti-cancer agent that selectively acts on CDK1, is in phase I/II clinical trial." (PMID 32201399, 2020). "Since our data demonstrated the alternative role of CDK1 to phosphorylate hTERT T249 for tumorigenesis, selective CDK1 inhibitors may have the profound impact on the treatment of aggressive cancers." (PMID 32214089, 2020). "In addition, we also illustrated that CHK1, CDK1, and PLK1 were associated with SLC16A7 in MDA-MB-231 and A549 cancer cells, providing a 75% validation ratio among four selected candidates." (PMID 31311925, 2019). "The unusual properties of CDK1 might be exploited to differentiate CDK1 from other CDKs in future cancer therapeutic design." (PMID 30472117, 2019). "Additionally, TIMELESS depletion slows cancer cell proliferation by inducing G2/M arrest as a result of DNA damage triggering inactivating phosphorylation of CDK1." (PMID 30629587, 2019). "Our results may affect the understanding of the process of cancerogenesis since CDC6 and its interactions with CDK1 play an important role in mitotic regulation and in cancer etiology." (PMID 31795221, 2019). "The downregulation of EZH2 observed in our cell lines, could be produced by the reduced expression of CDK1 after LUCAT1 knockdown that thus promotes the aberrant cell transformation to cancer cells." (PMID 31591432, 2019).
cancer (continued). "The regulation of the expression of the pluripotency regulators by CDK1 and KDM5B prompted us to investigate whether the cancer stem cell population is regulated by CDK1 and KDM5B." (PMID 31776402, 2019). "CDK1 is one of the key regulators, and its inhibition has potential as an anti-cancer treatment." (PMID 31569720, 2019). "CDK1 has been reported to be correlated with cancer growth and is a key cell cycle regulator." (PMID 30765611, 2019). "The overexpression of CDK1, TYMS, CDT1, and CCNA2 and the underexpression of PRKACB were associated with tumorigenesis, defective cell signaling, or aberrant metabolism in other cancers." (PMID 31205467, 2019). "In addition, pharmacological and genetic perturbations of CDK1 altered the expression of Mediumpurple2 genes in human cancer cell lines, and the expression levels of CDK1 and Mediumpurple2 genes were correlated under PD-like insult and levodopa treatment." (PMID 30886221, 2019). "Through genetic analysis based on loss of function of Cdk1 and Cdk2 along with conditional Myc expression, we show here the pivotal role of Cdk1 on p27 phosphorylation and its potential relevance for Cdk1-based synthetic lethal approaches to control Myc in cancer." (PMID 31822694, 2019). "The unusual properties of monomeric CDK1 might be exploited to differentiate CDK1 from other CDKs in future cancer therapeutic design." (PMID 30472117, 2019). "Upregulated SMC4 mRNA level could improve the sensitivity of Cdk1 to drive chromatin compaction at mitotic entry and increase the aggressiveness, proliferation, and dedifferentiation of cancer cells." (PMID 31871499, 2019). "Firstly, CDK1 can be the SL partner gene of the cancer genes KRAS and MYC." (PMID 29855504, 2018). "CDK1 gene’s major role in development and cancer is supported by many experimental studies." (PMID 30514202, 2018). "Our algorithm successfully ranks the CDK1 gene as the top gene for all cancer types analyzed here." (PMID 30514202, 2018). "In CDK1 highly-expressed cancer cells, a higher cell proliferation capability is observed, which is might partially responsible for pooror clinical outcomes in patients with this type of tumor." (PMID 29069733, 2017). "Furthermore, the similar effects can be detected in different cancer cell lines, indicating B220 activates the Cdk1/cyclin B1 complex in cancer cells." (PMID 28963527, 2017). "Zhang and his colleagues also discovered that BA-j, as a derivative of baicalein and selectively inhibited CDK1, could induce apoptosis in cancer cells via regulating reactive oxygen species." (PMID 29156780, 2017). "Moreover, we show that compromised CDK1 activity dramatically increases the efficacy of chemotherapeutic agents that kill cancer cells through perturbing DNA replication, including Olaparib, an FDA approved PARP inhibitor." (PMID 29207595, 2017). "Our results indicate that aberrant CDK1 signaling activation plays a role in cancer cell proliferation and may thus be a potential therapeutic target in the treatment of human cancer." (PMID 28869606, 2017). "Due to its higher expression in cancer cells, CDK1 might serve as not only a therapeutic target but also a prognosis marker." (PMID 29069733, 2017). "Considering its biological roles, CDK1 expression in HCC cells might reflect proliferation status and cancer stem cell properties, which are associated with the OS of HCC patients." (PMID 28434945, 2017). "Moreover, the results of the colony formation assay indicated that CDK1 activity was required for the cancer-promoting effects of KCTD12." (PMID 28869606, 2017). "The requirement of CDK1 for DNA replication and genome stability maintenance provides a new target that can be exploited to achieve a better efficacy of combined therapies against human cancers." (PMID 29207595, 2017). "Further, we show that CDK1 inhibition sensitizes cancer cells to different chemotherapeutic agents." (PMID 29207595, 2017).
cancer (continued). "In the case of checkpoint adaptation, the role of mitotic kinases such as Cdk1 may be re-evaluated with a view on genomic instability in cancer cells." (PMID 29113112, 2017). "Mostly, Cdk1′s function of nucleus for cell cycle is well known to be associated with cancer, but cytoplasmic Cdk1′s traits are not clearly identified, yet." (PMID 27385216, 2016). "Here we show a KRAS/CDK1 synthetic lethality that can be elicited with small molecule CDK1 inhibitors might also be added to the list of potential utilities for small molecule CDK inhibitors in cancer." (PMID 26881434, 2016). "Cytoplasmic Cdk1 expression was greater in cancer tissues than in normal tissues." (PMID 27385216, 2016). "Several cancer related PCGs were involved such as CDK1/2, BRCA1 and TGFBR2, suggesting that lncRNAs in the core subnetwork may mediate the tumorigenesis by competitively regulating these cancer driver genes in pan-cancers." (PMID 27580177, 2016). "Thus, as normal tissue progressed to cancer tissue, expression of Cdk1, particularly in the cytoplasm, increased considerably." (PMID 27385216, 2016). "The study also found that CDK1 protein was over-expressed in high malignant (grade III) cancer." (PMID 25129248, 2015). "As a key regulator of the cell cycle, CDK1 is a powerful therapeutic target for cancer inhibitors." (PMID 25997441, 2015). "Modulating Cdk1 level and its activity to cause TAZ degradation may be a potential target for the treatment of TAZ-induced drug resistance in cancers." (PMID 26183396, 2015). "Therefore, cells with highly activated Cdk1 are more sensitive to antitubulin drug treatments, while Cdk1 inhibitors can protect cancer cells from antitubulin-induced apoptosis." (PMID 26183396, 2015). "Interestingly, compared with the normal stage, the acrophase of CDK1 mRNA in precancerous lesions was earlier; however, it was delayed in the cancer stage." (PMID 25950458, 2015). "A priori the essential nature of CDK1 might be predicted to preclude its selection as a potential target for cancer treatment." (PMID 25864384, 2015). "The phosphorylation status of TAZ determines its function in antitubulin drug resistance and the Cdk1-TAZ signalling may be potential biomarkers for predicting the sensitivity of cancer patients to antitubulin drugs." (PMID 26183396, 2015). "Elevated Cdk1, Cdk2 and Cdk4 mRNA levels were detected in proliferating malignant tumors." (PMID 25900242, 2015). "Cancer cells with high Cdk1 expression appear to have greater cell proliferation capability, so that patients with this type of tumor might have poor outcomes." (PMID 25511643, 2014). "Several anticancer agents have been noted to mediate such G2/M phase arrest in cancer cells through multiple mechanisms: downregulation of CDK1-cyclin A/B complexes, inactivation of Cdc25C activity, and disruption of tubulin polymerization and spindle assembly." (PMID 25342427, 2014). "High Cdk1 expression was associated with poor prognosis for cancer relapse, especially in node-negative breast cancer patients." (PMID 25511643, 2014). "Dinaciclib is a potent CDK1, 2, 5 and 9 inhibitor being developed for the treatment of cancer." (PMID 25289887, 2014). "Our results suggested that Cdk1 might have a different prognostic role depending on the cancer type and the location of Cdk1 expression." (PMID 25511643, 2014). "The fact that high CDK1, low βTrCP phenotype was seen in a majority of tumors may reflect the proportion of high grade carcinomas in this tissue microarray." (PMID 25149538, 2014). "Furthermore, cancer cells harbouring CCNE1 gene amplification displayed a higher sensitivity to the CDK1, CDK2 and CDK9 small molecule inhibitor AZD5438 than cancer cells lacking CCNE1 gene amplification (t-test, P = 0.019)." (PMID 22433433, 2012). "The inhibition of cdk1 phosphorylation is one of alternative strategy which could selectively kill cancer cells and potentially be combined with DNA damaging agent such as curcumin." (PMID 23351311, 2012).
cancer (continued). "Indeed, over-expression of both cyclinB1 and CDC25, important regulators of CDK1 activity, are prognostic markers in colorectal and other cancers." (PMID 22108518, 2012). "CDK1, CDK4, and CDK6 have a diagnostic value in various cancers." (PMID 22333595, 2012). "Because deficiency in Cdk1 results in no cell division, CDK1 loss from cancer cells is unlikely a genetic or early event in tumorigenesis." (PMID 21887332, 2011). "Data derived from the NCI 60 human cancer cell line database suggests that the status of many components of the CDK1 machinery could potentially play a broad role in sensitivity to chemotherapy that is not only limited to NSCLC cell lines." (PMID 21887332, 2011). "Since upregulation of RGC-32 expression has been linked to numerous cancers, potentially through the role of RGC-32 as an activator of the mitotic CDK1/cyclin B1 complex, these results may implicate RGC-32 upregulation in EBV-mediated tumourigenesis." (PMID 22163048, 2011). "Under selective pressure for survival, cancer cells with low CDK1 activation might acquire advantages for expansion and metastasis." (PMID 21887332, 2011). "Thus, CDK1 might be a helpful molecular marker for the diagnosis of both types of cancer and can also help predict the prognosis of patients with cancer." (PMID 39991589, 2025). "Therefore, CDK1 is a potential therapeutic target for cancer treatment." (PMID 38464517, 2024). "Interrupting the Pin1/CDK1/pVHL axis results in decreased cancer cell proliferation, migration, invasion, and chemoresistance, and therefore it could be therapeutically valuable in treating cancers with wild-type VHL." (PMID 38727267, 2024). "In addition, inhibiting or targeting CDK1 may improve cancer therapy by overcoming immune evasion mechanisms." (PMID 38895552, 2024). "Because MiDAS is elevated in cells challenged with RS and is especially prevalent in aneuploid cancer cells with oncogene activation, inhibition of CDK1 may provide a therapeutic intervention in cancers with elevated TDP1 expression, which is known to cause chromosomal instability." (PMID 39014228, 2024). "Moreover, the phosphorylation of hTERT by CDK1 participates in cancer development." (PMID 38246945, 2024). "The CDK1/cyclin B complex effectively regulates mitochondrial dynamics, mitochondrial protein influx, and bioenergetics via the phosphorylation of mitochondrial and Bcl family proteins to sustain metabolic reprogramming in the face of increased energy requirements for cancer cell survival." (PMID 37569750, 2023). "Therefore, it is likely that that Frondoside A inhibits the proliferation and metastasis of cancer cells by down-regulating CDK1, CDC20, TOP2A and up-regulating CNN1.It should be noted that the free binding energy between Frondoside A and CDK1 was the lowest, measuring -10.7 kcal/mol." (PMID 38144520, 2023). "Moreover, the pharmacological inhibition of CDK1 by RO‐3306 markedly decreased the migration, invasion, the efficiency of mammosphere formation, metastasis and sensitized cancer cells to chemotherapeutic drugs in cells with the reconstitution of WT USP29." (PMID 36782089, 2023). "The mechanisms underlying NQO1/c-Fos/CKS1-mediated regulation of cell cycle progression in cancer cells were studied using siRNA approaches, overexpression systems, reporter assays, co-immunoprecipitation, pull-down assays, microarray analysis, and CDK1 kinase assays." (PMID 36793872, 2023).